ZNF418 (zinc finger protein 418)
Description:
Transcriptional repressor. May play a role as regulator of the ubiquitin-proteasome system and autophagy-lysosomal pathway (By similarity).
Synonyms: KIAA1956; FLJ31551; ZFP418
Tractability: PROTAC: ubiquitination databases record sites on it.
Gene: Protein-coding gene on chromosome 19 (57,921,882 to 57,935,402, reverse strand). Ensembl gene ENSG00000196724.
Subcellular location: Nucleus
Subcellular location (Human Protein Atlas): Nucleoplasm
Pathways (Reactome):
Gene expression (Transcription): Generic Transcription Pathway; Regulation of endogenous retroelements by KRAB-ZFP proteins
Gene Ontology:
Molecular function: DNA-binding transcription repressor activity; protein binding; DNA-binding transcription factor activity, RNA polymerase II-specific; RNA polymerase II cis-regulatory region sequence-specific DNA binding; DNA-binding transcription factor activity
Biological process: microautophagy; regulation of proteasomal ubiquitin-dependent protein catabolic process; regulation of transcription by RNA polymerase II; negative regulation of DNA-templated transcription; regulation of DNA-templated transcription
Cellular component: nucleus
Genetic constraint (gnomAD): Loss-of-function variants: 32 observed, 33.92 expected, observed/expected ratio (o/e) 0.94, 90% interval 0.71 to 1.27. The upper end of that interval is the gene's LOEUF score, 1.27, which puts it in group 5 of 6, group 1 being the genes least tolerant of losing a copy. Missense variants: 804 observed, 847.15 expected, observed/expected ratio (o/e) 0.95, 90% interval 0.89 to 1.01. Synonymous variants: 276 observed, 281.36 expected, observed/expected ratio (o/e) 0.98, 90% interval 0.89 to 1.08.
Homologues: Orthologues: chimpanzee ZNF418 (95% identical), macaque ZNF418 (87% identical), mouse Zfy1 (17% identical), mouse Zfy2 (16% identical), tropical clawed frog zfx (16% identical), rat Zfy1 (16% identical), zebrafish zfx (15% identical). Paralogues in human: ZNF587B (57% identical), ZNF551 (45% identical), ZNF256 (43% identical), ZNF552 (41% identical), ZNF304 (39% identical), ZNF792 (38% identical), ZNF549 (37% identical), ZNF548 (35% identical), ZNF586 (34% identical), ZIK1 (31% identical), ZNF773 (31% identical), ZNF772 (30% identical), and 26 more.
Diseases named in the same sentence as ZNF418 in open-access papers:
ZNF418 is named in the same sentence as 13 diseases in open-access papers, as found by Europe PMC text mining. Sharing a sentence is not in itself a finding about the gene and the disease. The quoted sentences say what the papers report.
gastric cancer (3 papers, 2021 to 2023). A primary or metastatic malignant neoplasm involving the stomach. "Only a few studies documented that ZNF418 negatively regulated transcription and the MAPK signaling pathway and that lower expression of ZNF418 was associated with poorer prognosis in gastric cancer." (PMID 36861126, 2023). "For example, high ZNF418 expression correlated with improved OS in gastric carcinoma, whereas its promoter hypermethylation showed a good discriminatory potential between high- and low-risk patient cohorts." (PMID 36547193, 2022). "At the same time, we found that zinc-finger protein 418 (ZNF418, context = -0.692), as a TOP3 prediction target gene, has been widely studied in tumors and plays an antitumor role in gastric cancer, liver cancer, and esophageal cancer." (PMID 34988117, 2021).
cardiac hypertrophy (1 paper, 2017). "This study aimed to investigated the effect and mechanism of zinc-finger protein 418 (ZNF418) on cardiac hypertrophy caused by aortic banding (AB), phenylephrine (PE) or angiotensin II (Ang II) in vivo and in vitro." (PMID 29065170, 2017). "Furthermore, several hypertrophic markers were detected to confirm the effect of ZNF418 deficiency on cardiac hypertrophy." (PMID 29065170, 2017). "To explore the effect of ZNF418 on pathological cardiac hypertrophy, we first detected the expression of ZNF418 in hearts of patients with DCM or HCM as well as hearts of cardiac hypertrophy mice." (PMID 29065170, 2017). "Then, the expression of ZNF418 was up-regulated or down-regulated in AB-induced cardiac hypertrophy mice and Ang II -induced hypertrophic primary cardiomyocytes." (PMID 29065170, 2017). "ZNF418 was markedly down-regulated in hearts of cardiac hypertrophy and hypertrophic primary cardiomyocytes." (PMID 29065170, 2017). "Then, the expression of ZNF418 was up-regulated or down-regulated in AB-induced cardiac hypertrophy mice and Ang II -induced hypertrophic primary cardiomyocytes, aimed to explore the effect of ZNF418 on cardiac hypertrophy in vivo and in vitro." (PMID 29065170, 2017). "An increasing number of researches have supported that down-regulated AP-1 protects ventricular cardiomyocytes against the induction of hypertrophy and apoptosis, indicating that ZNF418 may participate in the occurrence and development of cardiac hypertrophy." (PMID 29065170, 2017). "The present study confirms the down-regulation of ZNF418 in cardiac hypertrophy and fibrosis." (PMID 29065170, 2017). "Furthermore, we investigate whether AP-1 subunit c-Jun was involved in the development of cardiac hypertrophy regulated by ZNF418." (PMID 29065170, 2017). "Furthermore, ZNF418 may protect against the development of cardiac hypertrophy via inhibiting the activity of c-jun/AP-1." (PMID 29065170, 2017). "Interestingly, our study found that ZNF418 level was down-regulated in hearts of human or mice with cardiac hypertrophy as well as hypertrophic primary cardiomyocytes, which suggested that ZNF418 might be associated with cardiac hypertrophy." (PMID 29065170, 2017). "However, few studies had investigate the role of ZNF418 in cardiac hypertrophy." (PMID 29065170, 2017). "In the present study, we observed the expression of ZNF418 in hearts of DCM or HCM patients and aortic banding (AB)-induced cardiac hypertrophy mice in vivo, as well as in Ang II- or PE-induced hypertrophic primary cardiomyocytes in vitro." (PMID 29065170, 2017). "The expression of ZNF418 was markedly down-regulated in hearts of DCM or HCM patients, AB-induced cardiac hypertrophy mice, and Ang II- or PE-induced hypertrophic primary cardiomyocytes." (PMID 29065170, 2017). "The expression of ZNF418 in hearts of patients with dilated cardiomyopathy (DCM) or hypertrophic cardiomyopathy (HCM) and AB-induced cardiac hypertrophy mice, as well as in Ang II- or PE-induced hypertrophic primary cardiomyocytes was detected by western blotting." (PMID 29065170, 2017). "Consistently, after AB treatment for 4 weeks, the expression of ZNF418 was also lower, but ANP and β-MHC levels were higher in hearts of cardiac hypertrophy mice than hearts of sham mice (P < 0.05), and more significant changes were observed at 8week (P < 0.05)." (PMID 29065170, 2017). "However, the effect of ZNF418 on cardiac hypertrophy has not previously been investigated." (PMID 29065170, 2017).
clear cell renal cell carcinoma (1 paper, 2022). "High promoter methylation was also reported in the case of ZNF418 in laryngeal squamous cell carcinoma and ZNF540 in clear cell renal cell carcinoma." (PMID 36547193, 2022).
Insulin resistance (1 paper, 2021). Increased resistance towards insulin, that is, diminished effectiveness of insulin in reducing blood glucose levels. "The target genes TRDMT1, ZNF418, NAT1, and CDC7 have been experimentally associated through their expression levels or through knockouts, or are used as biomarkers, for waist circumference, BMI, obesity, or insulin resistance." (PMID 33957961, 2021).
tumor (3 papers, 2017 to 2025). "Eight genes (CDH23, HARS2, LLGL2, LTBP1, MAP6D1, MIPOL1, SCYL3, ZNF418) showed some degree of promoter methylation in at least one tumour, but only MIPOL1 exhibited probable homozygous methylation in more than one sample." (PMID 39794353, 2025). "In the same tumor type, ZNF418 promoter methylation was demonstrated as a potent diagnostic factor distinguishing between high- and low-risk groups of patients." (PMID 36547193, 2022). "Thus, it may be hypothesized that the decreased expression of ZNF540 and ZNF418 may affect tumor formation not only through various oncogene-related pathways but also via interfering with the immune response." (PMID 36547193, 2022). "Based on the UALCAN database, we observed a significant downregulation of ZFP28, ZNF132, ZNF418, ZNF426, ZNF540, and ZNF880 expression levels in primary tumor tissues compared to normal tissues." (PMID 36547193, 2022).
ZNF418 also shares sentences with these, for which no sentence is quoted: dilated cardiomyopathy (1 paper); esophageal cancer (1); hepatocellular carcinoma (1); hypertrophic cardiomyopathy (1); laryngeal squamous cell carcinoma (1); liver cancer (1); Obesity (1); Peters plus syndrome (1).